TMCO4 (transmembrane and coiled-coil domains 4)
Synonyms: DKFZp686C23231
Tractability: Antibody: UniProt predicts a signal peptide or a membrane-spanning region. PROTAC: ubiquitination databases record sites on it; its protein half-life has been measured.
Gene: Protein-coding gene on chromosome 1 (19,682,207 to 19,800,500, reverse strand). Ensembl gene ENSG00000162542.
Subcellular location: Membrane
Subcellular location (Human Protein Atlas): Endoplasmic reticulum
Gene Ontology:
Molecular function: protein binding
Cellular component: endoplasmic reticulum membrane; membrane
Genetic constraint (gnomAD): Loss-of-function variants: 56 observed, 66.45 expected, observed/expected ratio (o/e) 0.84, 90% interval 0.68 to 1.05. The upper end of that interval is the gene's LOEUF score, 1.05, which puts it in group 4 of 6, group 1 being the genes least tolerant of losing a copy. Missense variants: 753 observed, 835.02 expected, observed/expected ratio (o/e) 0.9, 90% interval 0.85 to 0.96. Synonymous variants: 308 observed, 346.82 expected, observed/expected ratio (o/e) 0.89, 90% interval 0.81 to 0.98.
Homologues: Orthologues: chimpanzee TMCO4 (99% identical), macaque TMCO4 (96% identical), pig TMCO4 (86% identical), dog TMCO4 (85% identical), guinea pig TMCO4 (85% identical), rabbit TMCO4 (85% identical), mouse Tmco4 (82% identical), rat Tmco4 (82% identical), tropical clawed frog tmco4 (62% identical), zebrafish tmco4 (53% identical), Caenorhabditis elegans F35D11.3 (38% identical).